IL18 (interleukin 18)
Diseases named in the same sentence as IL18 in open-access papers (continued):
Sharing a sentence is not in itself a finding about the gene and the disease.
tumor (continued). "Further, IMSA101 treatment induces IL-18 secretion which contributes to improved CART anti-tumor function." (PMID 38730243, 2024). "During pyroptosis, tumor cells secrete inflammatory cytokines that consist of IL-1β and IL-18, which attract macrophages and CTLs and promote tumor cell elimination." (PMID 39200381, 2024). "Follow-up work, however, has shed a positive light on the impact of IL-18-producing CAR T cells to augment tumor immunity, which inspired a clinical trial testing the impact of IL-18 secretion by anti-CD19 CAR T cells in patients." (PMID 39199630, 2024). "Notable decreased cytokines in the KEAP1-KO clones included IL-7R alpha, IL-18, IL-23, IL-31, and IL-33, which are pro-inflammatory and correlate with infiltration and activation of T cells and anti-tumor responses." (PMID 38542481, 2024). "Since it is known that IL‐1β and IL‐18 antagonism of tumour immune responses needs to be discussed depending on the type of cancer, it will not be discussed in detail here and has been summarized in an excellent review." (PMID 38652105, 2024). "Inflammatory vesicle‐dependent IL‐1β and IL‐18 exert anti‐tumour effects or pro‐tumour effects mainly depending on the TME." (PMID 38652105, 2024). "COM503 is a fully human high-affinity antibody which blocks the interaction between the IL-18 binding protein and IL-18, thereby freeing IL-18 in the tumor microenvironment to inhibit cancer growth." (PMID 39769266, 2024). "Congruently, IL-18 promotes angiogenesis and metastasis, leading to tumor progression and contributing to immune escape." (PMID 39335188, 2024). "It was later discovered that IL-18BP, acting as a secretory immune checkpoint, restricts the anti-tumor activity of IL-18." (PMID 38727246, 2024). "The utilization of MARCO-targeted antibodies induces the repolarization of TAMs, improves the level of IL-18, and strengthens the function of anti-tumor cells." (PMID 38590651, 2024). "In terms of the antitumor mechanism of CD39 antibodies, it has been indicated that CD39 blockade on macrophages and monocytes led to the activation of the NALP3 inflammasome and the release of IL-18 and IL-1β to exert anti-tumor effects." (PMID 39431011, 2024). "NLRP3 is a multiprotein complex that regulates macrophages, promoting secretion of pro-inflammatory cytokines such IL-18 and IL-1β by macrophages and this in turn was shown to optimize anti-tumor activity of NK cells and restrict tumor growth." (PMID 38533720, 2024). "The mRNA relative expression level of NLRP3, Caspase 1, GSDMD, IL-1β and IL-18 in XRZYBXD high dose group were significantly higher than those in the tumor model group by Q-PCR." (PMID 40046008, 2024). "Recently, IL‐18 has been considered as a major factor contributing to the formation of tumor microenvironment." (PMID 39031503, 2024). "IL-18 also exhibits anti-angiogenic and pro-lymphangiogenic properties that contribute to its anti-tumor activity." (PMID 38957317, 2024). "IL-18 engineered to avoid decoy-receptor binding enhances tumor rejection by anti-CTLA-4 in kidney cancer models through immune microenvironment remodeling." (PMID 39561007, 2024). "Their results showed a decrease in angiogenic capacity under hypoxic, tumor sinus-like conditions through negative regulation of interleukin IL-18." (PMID 39203369, 2024). "These NK cells activated by IL-18 demonstrate accelerated proliferation rates and heightened anti-tumor capabilities, including cytotoxicity, antibody-dependent cytotoxicity, and cytokine production, ultimately exerting anti-tumor effects." (PMID 39267832, 2024). "IL-18 anti-tumor activity is attributed among others to its ability to increase cytotoxicity and FAS ligand expression." (PMID 39769266, 2024). "Considering that NLRP3 can exert its tumor-promoting effects in DLBCL via its effector cytokine IL-18, we should comment on several studies investigating the prognostic significance of IL-18 expression in this setting." (PMID 38397043, 2024).
tumor (continued). "IL-18 cytokine creates a pro-inflammatory environment, recruiting bystander effector cells to the tumor location and enhancing their cytolytic activity." (PMID 38622705, 2024). "In colon cancer, activation of NLRP3 functions as a tumor suppressor by mediating the production of IL-18, which reinforces the killing activity of natural killer cells against metastatic tumor cells or down-regulates IL-22BP to suppress tumorigenesis." (PMID 39351349, 2024). "Although IL18 enhances the anti-tumor activity of CAR T cells, this cytokine has been linked to multiple inflammatory disorders in humans." (PMID 38745414, 2024). "For instance, rAd-IL-18 transgene-engineered DC vaccines have shown potential due to the unique ability of IL-18 to induce tumor-specific CTLs." (PMID 38528632, 2024). "Our results indicate that controlling the release of IL-18 by CAR-T cells also allows for controlling their antitumor potency in different tumor contexts." (PMID 39640015, 2024). "Notable, IL-15, IL-18, IL-1β, and TNFα in the host serum, potentially derived from the tumor microenvironment through various pathways, promoted sustained angiogenesis involving endothelial cells." (PMID 39451257, 2024). "IL-18 has shown anti-tumor activity in different preclinical models of cancer immunotherapy and chemotherapy through the activation of NK and T cell responses." (PMID 39769266, 2024). "IL-18 was shown to promote MDSC accumulation in the tumor microenvironment, leading to the suppression of CD4+ and CD8+ T cells, both in solid tumors and hematologic malignancies." (PMID 38397043, 2024). "Proinflammatory interleukins, such as interleukin-1β (IL-1β) and interleukin-18 (IL-18), play a significant role in cancer progression by modulating the tumor microenvironment and influencing various stages of tumor development." (PMID 39125732, 2024). "IL-18 also has anti-angiogenic and pro-lymphangiogenic properties contributing to its anti-tumor activity." (PMID 38957317, 2024). "Anti-tumor immune pathways such as IL-18 signaling pathway and TNF signaling pathway indicate its activated state of immune engagement." (PMID 39232806, 2024). "Aberrant activation of NLRP3 within the tumor microenvironment results in increased IL-1β and IL-18 secretion." (PMID 39882243, 2024). "CAR T cells with dual specificity are engineered in an attempt to potentiate their anti-tumor activity by incorporating an IL-18-producing construct into these cells." (PMID 39769266, 2024). "Based on bioinformatics analysis and cell biology experimental validation, we demonstrated that PTBP3 was able to promote exon skipping of IL‐18, which generated ΔIL‐18, an isoform expressed only in tumor tissues." (PMID 39116343, 2024). "In the B16-huCD19 tumor model, significantly more IL-18 and IL-23, as well as a trend towards more IL-22 and IFNγ was detected in serum of mice receiving combination treatment when compared to mice receiving CART alone." (PMID 38730243, 2024). "Concurrently, the lysis of tumor cells liberates additional inflammatory cytokines such as IL-18 and IL-6." (PMID 39521987, 2024). "The increase in IL-18 expression was noticeable only in the prostate tissue (glandular epithelium) with benign hyperplasia in the BPH + MetS group, what indicates the development of local inflammation." (PMID 37847180, 2023). "As chronic inflammation plays a decisive role in cancer development, NLRP3, IL-18, and IL-1β have been the focus of tumor researchers for over a decade." (PMID 36766797, 2023). "of human IL-1β promotes gastric tumorigenesis in transgenic mice, whereas a reduced tumor volume has been observed in IL-18-silenced nude mice." (PMID 37891577, 2023). "Inflammasomes can regulate immune cells and inflammatory factors, such as IL-1β and IL-18, to inhibit tumor growth, differentiation, and metastasis." (PMID 37705746, 2023). "A large number of studies have shown that IL18 has obvious anti-tumor effects in mouse tumor models and clinical experiments." (PMID 36707882, 2023).
tumor (continued). "In particular, IL-15, IL-12, and IL-18 secreted by DCs are strong inducers of NK cell proliferation, survival, and anti-tumor response, and are critically involved in the regulation of the anti-metastatic potential of NK cells." (PMID 37298470, 2023). "When we knocked down GSDMB in tumor cells, we found that pyroptosis was reduced and the IL‐18 cytokines in the supernatant decreased." (PMID 37587833, 2023). "In this regard, a significant increase in lymphocyte-activating IL2 was observed along with inflammasome-related IL1β and IL18, which play dual roles in cancer progression and anti-tumor immune responses." (PMID 36831596, 2023). "We also analyzed the connection of IL18 expression and its promoter methylation to the 23 immune cell lines in the tumor microenvironment." (PMID 36707882, 2023). "Currently, downstream BCR signaling molecules (PKD2 or BTK), tumor cell-derived IL-18 cytokine, and Breg-cell-mediated IL-35 are utilized to target pro-tumorigenic suppressor B cells in PDAC." (PMID 37033931, 2023). "As IL-18 has recently attracted attention in tumor biology, and the implication of IL-1β was extensively discussed elsewhere, the rest of this review will focus on the role of IL-18 in cancer progression." (PMID 37298187, 2023). "Depletion experiments revealed that the anti-tumor efficacy of IL-18 was dependent on both CD8+ T cells and NK cells." (PMID 37914685, 2023). "When tumor cells undergo pyroptosis, it is often attended by the release of the inflammatory cytokines IL-1β and IL-18, which possess pro-tumor and tumor-suppressive effects." (PMID 37705746, 2023). "Tumor cell-derived IL-1β and IL-18 elicited by NLRP3 are responsible for EMT through activating ERK and AKT signal resulting in strengthened migration." (PMID 36932407, 2023). "Among cytokines, βA most significantly increased the expression of Il1b, Il18 Il33, and Il15, both within tumor cells and fibroblasts." (PMID 38304252, 2023). "Nonetheless, we found 46 genes that carried either genomic or transcriptional alterations in all three resistant tumor groups, including 8 genes (Parp3, Gstm1, Il18, Padi4, Dnmt3b, Psrc1, Rif1, and Ankrd26) involved in DDR." (PMID 37209095, 2023). "To validate IL18 promoter methylation in tumor tissues, we analyzed these 6 methylation sites in IL18 promoter in TCGA database and anther two GEO datasets." (PMID 36707882, 2023). "Our previous studies have shown that the Th17-like neutrophil subpopulation that specifically secretes IL-17 after induction by IL-23 or the IL-23/IL-18 combination has the characteristics of promoting tumor growth and inflammation." (PMID 38137369, 2023). "For DCs and macrophages, secretion of IL-1β and IL-18 is accompanied by antigen presentation or T cell recruitment, while inflammasome activation in tumor cells is accompanied by immunosuppressive signals such as PD-1/PD-L1." (PMID 36932407, 2023). "IL-18, a pro-inflammatory cytokine, influences the tumor microenvironment, tumor progression, metastatic dissemination, and sensitive resistance." (PMID 36882663, 2023). "Consistent with the findings obtained from tumor-bearing lung tissues, NR1D1 deficiency led to increased mRNA expression of Nlrp3, Il1β, and Il18 in AM, as well as increased protein expression of NLRP3 and cleaved caspase-1 in both AM and normal lung tissues." (PMID 37524704, 2023). "So far, the researches on the role of IL18 in tumors have mainly focused on the promotion or inhibition of tumor development or immune infiltration mediated by IL18 through regulating related signaling pathways." (PMID 36707882, 2023). "Recent research has demonstrated the way inflammasomes protect against tumors by activating anti-tumor immunity through IL-1β and IL-18." (PMID 37705746, 2023). "Histological grades were found to have a positive correlation with IL-18 expression in immune-stromal cells of the tumor (x2=14.808, P=0.001)." (PMID 38031068, 2023).
tumor (continued). "IL-18 increases the activation and cytotoxicity of T cells and NK cells, as evidenced in tumor models." (PMID 37298187, 2023). "IL‐18 is normally expressed in cancerous tissues, with a significantly higher percentage of expression in normal tissues than in tumor tissues." (PMID 35789548, 2023). "In human tongue squamous cell carcinoma cells, overexpression of IL18 led to apoptosis of tumor cells and decreased Ccnd1 expression." (PMID 38139000, 2023). "IL‐18 plays a dual role in cancer by promoting tumour development, progression, invasion, migration and metastasis." (PMID 37849388, 2023). "Even GC presenting in the tumor microenvironment together with IL-12, IL-15, and IL-18 induces the de novo expression of PD-1 on NK cells, which are associated with a strong immunosuppressive phenotype." (PMID 37114049, 2023). "After differentiated for 6 days, P-CIML-NK (PBMCs were primed with IL-12, IL-15, and IL-18) and P–c-NK (PBMCs were primed with low concentration IL-15) cocultured with tumor targets for 6 h and then detected by flow cytometer." (PMID 36932395, 2023). "The attenuated hematopoietic cell-derived IL-1β and IL-18 at the tumor site of Nlrp3−/− mice are found to be the key for inflammation and tumorigenesis." (PMID 36932407, 2023). "This review will focus on the role of the purinergic receptor P2RX7 in the control of tumor growth, through its ability to modulate antitumor immunity by releasing IL-18." (PMID 37298187, 2023). "IL18 signaling has been reported to be either pro-tumorigenic or suppressive in tumor development and progression." (PMID 36980301, 2023). "This is in agreement with other work showing a strong antitumor activity of IL-18 as well as its potential as a biomarker for tumor progression and patient outcomes." (PMID 37298187, 2023). "Genes associated with a pro-inflammatory tumour microenvironment included TNF, IL6, IL18, NLRP3, IL1B and CASP1 which were also comparable between sporadic and NF2-SWN VS samples." (PMID 37680691, 2023). "Apparently, the MSCs-secreting IL-18 cells were able to restrain tumor cell proliferation and enhance the antitumor efficacy by triggering immune cytokines and immunocytes." (PMID 36742134, 2023). "Reduction of intestinal IL-18 levels in NLRP3 and caspase-1-deficient mice exposed to AOM/DSS showed that recombinant IL-18 prevented tumor development." (PMID 37081882, 2023). "CD4+ T cell-derived or exogenous IL-18 promotes proliferation and anti-tumor activity of CD8+ T cells and chimeric antigen receptor (CAR)-T cells." (PMID 36932407, 2023). "DEX treatment also decreased the levels of pro-inflammatory cytokines, including IL-1β, TNFα, IL-10, and IL-18, which are major tumor growth promoters." (PMID 37528154, 2023). "Since IL-18 is likely to be beneficial for anti-tumor immunity, recombinant IL-18 has been applied in several clinical trials such as NCT00659178, NCT00107718, and NCT00500058." (PMID 36932407, 2023). "The elevated levels of SASP by senescent T cells, such as IL-6, IL-8, and IL-18, promote tumor development and suppress antitumor immunity, regulating the tumor microenvironment through proinflammatory and anti-inflammatory cytokines." (PMID 38087369, 2023). "IL18, an important immune factor, is involved in various inflammatory responses and the regulation of tumor cells in the tumor microenvironment (Yasuda, Nakanishi & Tsutsui, 2019)." (PMID 38025749, 2023). "In this study, a significant reduction in NLRP3, ASC, IL-1β, and IL-18 expression was shown in the tumor’s samples from BAY-117082-treated mice compared to the OSCC group." (PMID 37345134, 2023). "IL18 exerts inflammation-dependent tumor-suppressive effects largely by promoting the differentiation, activity and survival of tumor-infiltrating T cells." (PMID 37575948, 2023).
tumor (continued). "Inhibiting CD39, an ecto-enzyme converting extracellular ATP to AMP, through antibody activates NLRP3 inflammasomes leading to IL-18 secreting that expands intra-tumor effector CD4+ and CD8+ T cells." (PMID 36932407, 2023). "Early evidence suggested that IL-18 has anticancer effect on tumour, which stimulated the cytotoxicity of natural killer cells (NKs) and enhanced the immune response of CD8+T lymphocytes (CD8+T)." (PMID 37871286, 2023). "As it was reported that DNA methylation was closely related to tumor microenvironment, we further investigated the potential of IL18 and promoter methylation and expression in immune regulation." (PMID 36707882, 2023). "In this study, we found that IL18 promoter was generally aberrantly methylated in RCC tumor tissues compared to the normal tissues." (PMID 36707882, 2023). "IL-18 helps repair the epithelial barrier to counteract damage, and after AOM-DSS induction, IL-18-/- mice were more likely to develop tumors than control mice, indicating that IL-18 has potential anti-tumor effects." (PMID 37497237, 2023). "It has been reported that IL-18 induces the differentiation of T-helper 1 (Th1) and T-helper 17 (Th17) cells, resulting in anti-tumor effects." (PMID 37705746, 2023). "The mRNA expression of IL-10 and IL-18 in tumor tissues was assessed by quantitative polymerase chain reaction (qPCR)." (PMID 37528154, 2023). "Further investigation into the mechanism of MSU-42011 is necessary to determine if Il-18 is a critical mediator of anti-tumor immune response, and if it can be used as an indicator of response to therapy." (PMID 36901727, 2023). "We observed that IL-10 and IL-18 expression in tumor tissue was significantly decreased in the DEX-treated group compared with the saline-treated group." (PMID 37528154, 2023). "Memory-like NK cells (MLNK) induced by IL-12, IL-15, and IL-18 have shown enhanced and prolonged responses to tumor re-stimulation, making them an attractive candidate for adoptive cellular immunotherapy." (PMID 37207215, 2023). "CD39 blockade augmented exATP/P2X7-mediated pro-inflammatory anti-tumor response and release of IL-18, which facilitated increased infiltration of intra-tumor Teff cells and overturned anti-PD-1 resistance." (PMID 36741002, 2023). "In a mouse CRC-liver metastasis model, the NLRP3 inflammasome increases IL-18 secretion, promotes maturation of hepatic NK cells, increases FasL expression, and Fas/FasL interaction can exert cytotoxicity on tumor cells." (PMID 37081882, 2023). "In the Panc02-lucifer-cell- orthotopic PDAC mouse model, the pairing of IL-18 inhibitor with PD-1/PD-L1 blockade inhibited tumor development and metastasis." (PMID 37033931, 2023). "Preclinical studies have shown that IL-18 is required to inhibit tumor growth using either il18-/- or il18r1-/- mice, or even recombinant IL-18 administration." (PMID 37298187, 2023). "IL-18 expression is elevated in the blood serum of CRC patients and is associated with tumor size, histological grade, and cancer cell metastasis, making it a potential indicator to predict CRC patients’ prognosis and survival time." (PMID 37176567, 2023). "In the liver metastatic colon cancer model, IL-18 is required for the suppression of Nlrp3 inflammasome on tumor growth and its promotion of intratumoral NK cell maturation and tumoricidal activity." (PMID 36973277, 2023). "In response to PD-L1 blockade, the emergence of PD-1+A2AR- cells correlates with successful therapeutic responses, whilst IL-18 is identified as a cytokine that potently upregulates A2AR and synergizes with A2AR deficiency to improve anti-tumor immunity." (PMID 37914685, 2023). "IL-18, as the main immunoregulatory cytokine, plays an important role as a factor in anti-infectious and anti-tumor protection of the body." (PMID 37175946, 2023). "This supports the predictive value of plasmatic IL-18, since it can be released from tumor and immune cells." (PMID 37298187, 2023).